GCKR (glucokinase regulator)
Diseases named in the same sentence as GCKR in open-access papers (continued):
Sharing a sentence is not in itself a finding about the gene and the disease.
hypertriglyceridemia (continued). "A recent study highlighted the clinical relevance of the collective burden of rare alleles in GCKR, reporting that non-synonymous variants with an MAF of <0.01 in the GCKR gene are enriched in cases of extreme hypertriglyceridemia." (PMID 35328045, 2022). "A GWA study of individuals with hypertriglyceridemia has shown that common variants in 4 genetic loci (APOB, LPL, GCKR, and APOA5) are significantly related to increased TG levels." (PMID 35999587, 2022). "Utilizing sequence data from 458 individuals with hypertriglyceridemia and 333 controls with normal plasma triglyceride levels, we investigated these issues using GCKR, encoding glucokinase regulatory protein." (PMID 24879641, 2014). "Our review firstly introduces the biological function of the GCKR gene and its encoding protein GKRP and then describes the GCKR variants in different diseases, such as hypertriglyceridemia and NAFLD, revealing that GCKR/GKPR is strongly associated with metabolic diseases." (PMID 41150798, 2025). "Although rare loss-of-function GCKR variants do not consistently cosegregate with hypertriglyceridemia, their influence on lipid levels should not be overlooked." (PMID 41150798, 2025). "Several reports have shown GCKR rs146175795 (p.Val103Met) in patients with hypertriglyceridemia." (PMID 35328045, 2022). "Accordingly, while GCKR variation is associated with alterations in triglyceride levels, such variants are neither necessary nor sufficient to cause hypertriglyceridemia." (PMID 24879641, 2014). "This reflects GCKR’s central role in liver GLU sensing and fat production, driving both hyperglycemia/hypertriglyceridemia (raising TyG) and liver fat buildup in MASLD." (PMID 41056021, 2026).
steatosis (18 papers, 2013 to 2025). Increased lipid within the cytoplasm of cells. "Notable single nucleotide polymorphisms (SNPs), including PNPLA3 rs738409, TM6SF2 rs58542926, MBOAT7 rs641738, and GCKR rs1260326, are consistently linked to steatosis, inflammation, and fibrosis in MASLD." (PMID 40943344, 2025). "Genetic variants in GKPR, glucokinase regulatory protein were associated to steatosis and NAFLD and the gene was also downregulated in the differential expression analysis of this study." (PMID 38365720, 2024). "• rs1260326-T variant decreases GCKR ability to inhibit glucokinase → increased hepatic glucose uptake, decreased fatty acid oxidation and enhanced lipogenesis → the progression of steatosis or levels of circulating lipids." (PMID 36035124, 2022). "The GCKR rs1260326 variant causes a loss‐of‐function of a regulatory enzyme that leads to increased de novo hepatic lipogenesis, thus increasing the risk of steatosis." (PMID 36166317, 2022). "The specificity of variant-metabolite associations were compared to metabolite associations with ultrasound-defined steatosis, gene variants linked to liver fat (in GCKR, PPP1R3B and LYPLAL1) and gene variants linked to cirrhosis (in HFE and SERPINA1)." (PMID 32720691, 2020). "In this study, besides confirming the associations between PNPLA3 C>G SNP and steatosis/lobular inflammation, for the first time we also highlighted the potential impact of GCKR C→T SNP on liver fibrosis in an European cohort of histologically diagnosed NAFLD patients." (PMID 24498332, 2014). "Among these gene variants, the glucokinase regulatory protein (GCKR) has been further confirmed as linked with steatosis (identified either by ultrasonography, by magnetic resonance, or by computed tomography) in children, in obese patients, and in populations of different ethnicity." (PMID 24498332, 2014). "Thus, GCKR (rs780094) may play some role in the development of steatosis under cART, since this polymorphism seems to influence serum lipid traits in HIV-infected patients." (PMID 28594920, 2017). "Variants in PNPLA3, GCKR, MBOAT7, and TM6SF2 were variably associated with liver injury and steatosis markers, with cohort-specific effects." (PMID 40943344, 2025). "Hispanic ethnicity and genetic polymorphisms in PNPLA3, TM6SF2, GCKR, MBOAT7, and HSD17B13 are associated with steatosis-related lipotoxicity and oxidative DNA damage, which can contribute to hepatocarcinogenesis." (PMID 40995256, 2025). "Evaluation of the interaction of PNPLA3 with other genetic variants influencing steatosis and NASH, including GCKR, ENPP1 and IRS-1, SOD2, KLF6, LPIN1, and possibly other SNPs will be instrumental to achieve these goals." (PMID 23394097, 2013). "Therefore, decreased GCKR activity contributes to the progression of steatosis or levels of circulating lipids." (PMID 36035124, 2022). "We aimed to assess whether GCKR rs780094 C→T SNP influences the expression of steatosis, lobular inflammation and fibrosis in NAFLD patients, after correction for PNPLA3 genotype." (PMID 24498332, 2014). "Obviously, the lack of these data could partially affect the interpretation of our results, and in particular of the significance of the real effect of GCKR SNP on steatosis." (PMID 24498332, 2014). "The glucokinase regulatory protein (GCKR) rs1260326 C>T (P446L) variant augments glucose‐driven de novo lipogenesis, and the membrane bound O‐acyltransferase domain‐containing 7 (MBOAT7) rs641738 C>T allele upsets phospholipid remodelling, both contributing to steatosis and inflammation." (PMID 41255342, 2025). "By contrast we did not identify any association between severity of steatosis and GCKR genotype." (PMID 24498332, 2014).
non-alcoholic fatty liver disease (13 papers, 2012 to 2026). "The rs1260326 polymorphism mapped to GCKR was reportedly associated with non-alcoholic fatty liver disease and cardiovascular disease-related phenotypes." (PMID 38785970, 2024). "Previous studies have found that polymorphisms in GCKR (rs780094) are associated with non-alcoholic fatty liver disease in multiple populations." (PMID 34830198, 2021). "Association of the GCKR rs780094 genotype and liver damage as evaluated by unadjusted and adjusted models in 366 Patients with Non-alcoholic Fatty Liver Disease." (PMID 24498332, 2014). "Human liver biopsies from a nonalcoholic fatty liver disease (NAFLD) study that had been genotyped for GCKR rs780094 (n = 48) were additionally genotyped for rs1260326C > T, with 23 and 17 confirmed CC and TT, respectively." (PMID 37031802, 2023). "In contrast, the genes PNPLA3 (adiponutrin), GCKR (glucokinase regulator) and TRIB1 (tribbles homolog 1) were associated with fibrosis phenotypes in non-alcoholic fatty liver disease, with PNPLA3 demonstrating the most consistent effects across studies." (PMID 24586654, 2014). "The mutation or gene variants of GCKR was reported to be associated with several clinical manifestation, such as T2DM, nonalcoholic fatty liver disease (NAFLD), familial combined hyperlipidemia (FCHL), coronary artery disease, ischemic stroke, gout and chronic kidney disease." (PMID 33292424, 2020). "Further studies with larger sample size could be helpful in holding more relevant findings and interventional designs are needed to determine the effects of dietary compounds in different GCKR genotypes in nonalcoholic fatty liver disease." (PMID 31924263, 2020). "Several SNPS, such as rs11591147 in PCSK9, rs1260326 in GCKR, rs10455872 in LPA, rs964184 in ZPR1, rs58542926 in TM6SF2, and rs182611493 in MAU2 have been clinically associated with multiple metabolic disorders, including coronary heart disease, hyperlipidemia, non-alcoholic fatty liver disease." (PMID 41608459, 2026).
Hyperglycemia (11 papers, 2012 to 2026). An increased concentration of glucose in the blood. "Several studies have also reported that LPA variants that are considered risk factors for cardiovascular disease and GCKR variants are associated with hyperglycemia." (PMID 35999587, 2022). "In conclusion, our study showed that compared to the carriers of the T allele, the carriers of the C allele of rs780094 of GCKR had lower lactate levels in the fasting state but higher lactate increment relative to fasting lactate during hyperglycemia in humans." (PMID 30375486, 2018). "Overall, our results suggest that increased lactate levels relative to fasting lactate in carriers of the C allele of rs780094 upon hyperglycemia may be explained by higher GCKR expression." (PMID 30375486, 2018). "However, like the cat, GCKR knockout mice are susceptible to stress-induced hyperglycemia and exhibit mild glucose intolerance compared with wild-type that express GCKR." (PMID 24348462, 2013). "Variants in the GCK and GCKR genes can disrupt the balance of the GCK/GKRP complex, leading to abnormal glucose concentrations and hyperglycemia." (PMID 38396716, 2024).
coronary artery disease (8 papers, 2016 to 2026). "The MEDLINE and EMBASE databases were searched for studies reporting on the association between GCKR variants (rs1260326, rs780094, and rs780093) and coronary artery disease (CAD), estimated glomerular filtration rate (eGFR), and chronic kidney disease (CKD)." (PMID 30352097, 2018). "Examining the associations between individual urate genetic risk loci and the related disease outcomes highlighted two loci, GCKR and PTPN11/ATXN2, which drive their association with hypercholesterolemia, hypertension, and ischemic heart disease." (PMID 31626644, 2019). "Moreover, we prudently excluded three SNPs, namely rs1260326 in GCKR, rs34894639 in PPP2R3A, and rs2943652 in NEU2, owing to their known pleiotropic effects on a range of human traits, including T2DM, coronary artery disease, BMI, and triglycerides, as evidenced by PhenoScanner database searches." (PMID 37049421, 2023).
hepatocellular carcinoma (8 papers, 2022 to 2026). A malignant tumor that arises from hepatocytes. "Moreover, the rs641738 C>T variant in the MBOAT7 gene as well as the loss-of-function rs1260326 C>T variant in the GCKR gene are related to inflammation, increased susceptibility to NASH, fibrosis, and hepatocellular carcinoma (HCC)." (PMID 35739957, 2022).
Cirrhosis (7 papers, 2020 to 2026). A chronic disorder of the liver in which liver tissue becomes scarred and is partially replaced by regenerative nodules and fibrotic tissue resulting in loss of liver function. "Over 50% of cirrhosis patients had at least one risk variant in PNPLA3, MBOAT7 and GCKR, while 13.0% had at least one risk variant in TM6SF2." (PMID 36854015, 2023).
Hypertension (7 papers, 2012 to 2025). The presence of chronic increased pressure in the systemic arterial system. "The GCKR variant associated with multiple lipid phenotypes was also observed to increase the risk of hypertension (OR=1.26 [1.00, 1.59] p= 0.05)." (PMID 23150898, 2012). "The GCKR variant demonstrated strong associations with total-cholesterol and triglyceride levels and nominal associations with hypertension and LDL-Cholesterol, however previous reports of associations with fasting glucose levels were not confirmed in this study." (PMID 23150898, 2012). "There was also a signal on chromosome 2 that resolved into two independent signals in KCNKR for hypertension and GCKR for CKD, within 850 kb of each other." (PMID 40538118, 2025).
Crohn disease (6 papers, 2015 to 2022). A gastrointestinal disorder characterized by chronic inflammation involving all layers of the intestinal wall, noncaseating granulomas affecting the intestinal wall and regional lymph nodes, and transmural fibrosis.
Hypercholesterolemia (6 papers, 2018 to 2026). An increased concentration of cholesterol in the blood. "Additionally, phenome-wide Mendelian randomization (Phewas) analysis indicated potential therapeutic benefits of targeting GCKR, such as reducing the risk of pure hypercholesterolemia and alcohol intake frequency." (PMID 38782984, 2024).
hyperlipidemia (5 papers, 2022 to 2026). "This variant correlates with the expression of GCKR and the occurrence of hyperlipidemia, with a minor allele frequency (MAF) ranging from 0.2 to 0.4 according to various databases." (PMID 41150798, 2025). "A study in 2016 reported that a patient carried three distinct GCKR mutation sites and suffered from severe hyperlipidemia following her pregnancy." (PMID 41150798, 2025). "Specifically, increased levels of GCKR (odds ratio [OR] = 0.42, 95% confidence interval [CI], 0.37–0.47; P = 3.64e-45) and TIMD4 (OR = 0.60, 95% CI, 0.50–0.72; P = 4.43e-08) decreased the risk of hyperlipidemia." (PMID 39474612, 2024). "Nevertheless, only a small portion of variants, i.e., among the >100 hyperlipidemia-associated loci identified by GWAS, have been elucidated with respect to their impact on the regulation of the lipid metabolism factors SORT1 and GCKR as well as VLDLR and ELOVL214–17." (PMID 35046404, 2022). "Among these hyperlipidemia-associated five loci, a mechanism has been established for only rs780092 (2p23.3), owing to LD with rs780094 (r2 = 0.45 in EAS of the 1000 Genomes Project); rs780094 facilitates the binding of transcription factor FOXA2 to regulate GCKR expression." (PMID 35046404, 2022).
hyperuricemia (5 papers, 2022 to 2025). An abnormally high level of uric acid. "The study explored the genetic association of the common functional variants of GCKR with the serum UA levels in Taiwanese adolescents because of the uniqueness of hyperuricemia in teenagers." (PMID 35365700, 2022). "In the recessive model, GCKR SNP (rs780094) was shown to be associated with the risk of hyperuricemia in men in the Uyghur population of Xinjiang in China (p = 0.015, OR = 1.311)." (PMID 35813212, 2022). "Recently, genome-wide association studies have revealed a positive association between hyperuricemia and GCKR variants in adults." (PMID 35365700, 2022). "We found that the participants with specific GCKR polymorphisms showed a higher risk for hyperuricemia and other metabolic traits on the basis of gender differences in Taiwanese adolescents." (PMID 35365700, 2022). "An European study showed that alcohol drinking by individuals with GCKR rs780094 strongly influenced the risk of hyperuricemia compared with that noted in the case of no alcohol consumption." (PMID 35365700, 2022).
liver fibrosis (5 papers, 2014 to 2025). "In patients with NAFLD, GCKR rs780094 C>T is associated with the severity of liver fibrosis and with higher serum triglyceride levels." (PMID 24498332, 2014). "The association of GCKR rs1260326 has been repeatedly reported especially in NAFLD with a considerable contribution to liver damage and hepatic fibrosis." (PMID 37829557, 2023). "Single nucleotide polymorphism of the GCKR rs1260326 alters the adiponectin function and influences the lipogenesis pathway to increase susceptibility and severity of NAFLD and hepatic fibrosis." (PMID 37829557, 2023). "A different variant of GCKR (rs780094 C>T, intron variant) was associated with high triglyceride levels, development of NAFLD, and severity of liver fibrosis, confirming the relevance of the GCKR gene status in the disease." (PMID 34069012, 2021). "In conclusion, this study on a large cohort of patients with histological diagnosis of NAFLD, showed an independent link between GCKR SNPs and significant hepatic fibrosis." (PMID 24498332, 2014). "This is the first study to investigate the relationship between the PNPLA3 rs738409, TM6SF2 rs58542926, GCKR rs1260326 and rs780094, MBOAT7 rs641738, HSD17B13 rs72613567, and MTARC1 rs2642438 polymorphisms in the Brazilian population with MASLD and liver fibrosis." (PMID 40650184, 2025). "In addition, this is the first study to investigates the relationship between the rs738409 (PNPLA3), rs58542926 (TM6SF2), rs1260326 and rs780094 (GCKR), rs641738 (MBOAT7), rs72613567 (HSD17B13), and rs2642438 (MTARC1) polymorphisms in the Brazilian population with MASLD and hepatic fibrosis." (PMID 40650184, 2025). "Although this study was not designed to clarify the pathogenic link between GCKR SNPs and liver fibrosis in NAFLD, some hypotheses can be provided." (PMID 24498332, 2014).
chronic kidney disease (4 papers, 2013 to 2020). Impairment of the renal function secondary to chronic kidney damage persisting for three or more months. "Conversely, the steatogenic allele in GCKR locus seems to protect against the development of chronic kidney disease among T2D individuals, consistently with the GCKR‐related hypoglycaemic effect observed in nondiabetic individuals." (PMID 33102799, 2020).
fibrosis (4 papers, 2014 to 2024). the formation of excess fibrous connective tissue in an organ or tissue in a reparative or reactive process. "Fifty-two per cent (50/97) of metabolites associated with NASH-fibrosis variants were also associated with liver fat variants, again the majority (86%, 43/50) were PC species due to similarity between GCKR and TM6SF2 metabolite associations." (PMID 32720691, 2020). "Variants of other genes, such as glucokinase regulatory protein (GCKR), which regulates glucose metabolism and de novo lipogenesis, have been correlated with NAFLD-associated fibrosis." (PMID 38398781, 2024). "When histological variables were removed from the model, >F1 fibrosis was independently linked to female gender (OR 1.77, 95% CI 1.05–2.99, p = 0.03), BMI (OR 1.08, 95% CI 1.02–1.14, p = 0.008), HOMA (OR 1.16, 95% CI 1.05–1.28, p = 0.004), and GCKR C>T SNP (OR 1.88, 95% CI 1.33–2.66, p<0.001)." (PMID 24498332, 2014).
Gestational Diabetes Mellitus (4 papers, 2020 to 2025). "Some studies reported that GCKR rs780094 was associated with the susceptibility of gestational diabetes in Malaysian population and Brazilian." (PMID 33292424, 2020). "Apart from T2DM, polymorphisms of GCKR was also a susceptibility gene of gestational diabetes." (PMID 33292424, 2020).
Hypoglycemia (4 papers, 2018 to 2025). A decreased concentration of glucose in the blood. "Further, F1P stimulates rapid glucose uptake by releasing glucokinase regulatory protein (GKRP), causing acute hypoglycemia, intracellular ATP depletion and uric acid generation." (PMID 37892451, 2023). "The glucose‐lowering effects induced by these GCKR small‐molecule disruptors was restricted to diabetic and non‐normoglycaemic animals, suggesting an advantage in preventing adverse effects of drug treatment, which may lead to hypoglycemia." (PMID 39921581, 2025).
Alcohol Use Disorder (3 papers, 2019 to 2024). "GCKR has been identified as one of the genes associated with alcohol use disorders." (PMID 39734669, 2024). "Moreover, it exhibits a positive genetic correlation with SCZ, indicating a potential connection between GCKR and SCZ within the framework of alcohol use disorders." (PMID 39734669, 2024).
lipid metabolism disorders (3 papers, 2023 to 2026). "The intronic variant GCKR rs780094 is associated with a variety of lipid metabolism disorders that increase fat production by inducing glycolysis." (PMID 40806538, 2025). "Therefore, it is necessary to understand the role of GCKR polymorphisms in sepsis-associated lipid metabolism disorders." (PMID 41608459, 2026).
alcohol dependence (2 papers, 2021 to 2023). Physical and psychological dependence on alcohol. "JCAD, KLB, and GCKR have also been associated with alcohol dependence as assessed with the AUDIT." (PMID 34135785, 2021).
atherosclerosis (2 papers, 2016 to 2022). A disease characterized by the build-up of fatty material and calcium deposition in the arterial wall resulting in partial or complete occlusion of the arterial lumen. "In addition, we evaluated the potential relationship between HNF1A rs1183910, LEPR rs4420065, GCKR rs1260326, NLRP3 rs12239046, IL1F10 rs6734238, PPP1R3B rs9987289, ASCL1 rs10745954, HNF4A rs1800961 and SALL1 rs10521222 polymorphisms and CV events or subclinical atherosclerosis in RA patients." (PMID 27534721, 2016).